AQP9 (aquaporin 9)
Diseases named in the same sentence as AQP9 in open-access papers (continued):
Sharing a sentence is not in itself a finding about the gene and the disease.
diabetes (11 papers, 2012 to 2024). "Studies on experimental diabetes in rodents as well as tissue samples from patients with diabetes have shown an increase in the level of AQP9 mRNA and protein." (PMID 29566083, 2018). "The possibility should be considered that an upregulation of Aqp9 contributes to the increased prevalence of Parkinson’s disease among patients with diabetes mellitus type 2." (PMID 29566083, 2018). "Recent data indicate that AQP9 regulates Leydig cell steroidogenesis in diabetes." (PMID 38338845, 2024). "The coordinated regulation of glycerol channels in adipose tissue (AQP7) and the liver (AQP9) has been suggested as an important contributor to the pathophysiology of type-2-diabetes mellitus, as it would provide glycerol for hepatic synthesis of glucose and triglycerides." (PMID 33193093, 2020). "Using an AQP9-knockout mice model it has been shown that AQP9 is important for hepatic glycerol metabolism and may play a role in glycerol and glucose metabolism in diabetes mellitus." (PMID 23185530, 2012). "In the streptozotocin-induced diabetes model, the severity of NASH is directly proportional to the level of AQP9 in liver tissue." (PMID 34659635, 2021). "Variable results have been observed regarding the hepatic expression profile of AQP9 in obese subjects with type 2 diabetes mellitus (T2D) and obese subjects with no impairment of their glucose tolerance." (PMID 27409609, 2016).
leukemia (11 papers, 2012 to 2024). A malignant (clonal) hematologic disorder, involving hematopoietic stem cells and characterized by the presence of primitive or atypical myeloid or lymphoid cells in the bone marrow and the blood. "In conclusion, the present study identified that the glycerol content of leukemia stem cells was significantly lower than that of normal bone marrow stem cells, while both cell types were deficient of AQP9." (PMID 24959239, 2014). "Aquaporin-9 (AQP9) expression is associated with arsenic sensitivity in leukemia cells." (PMID 28640255, 2017). "It has been suggested that aquaporin 9 (AQP9), a member of the aquaporin superfamily, is responsible for AsIII uptake into leukemia cells and has become a promising target in the development of treatment strategies against APL." (PMID 39768226, 2024). "It has been reported that the uptake of ATO into leukemia cells depends on AQP9, a transmembrane transporter belonging to the aquaporin family." (PMID 35590355, 2022). "Previous investigations had shown that indirubin and tanshinone IIA up-regulated AQP9 expression and augmented the anti-leukemia effect of As2O3 as present in the Realgar-Indigo naturalis formula." (PMID 25953102, 2015). "The aim of the present study was to investigate the AQP9 expression in normal and leukemic HSCs, and to identify the possible effects of AQP9 in leukemia progression." (PMID 24959239, 2014). "The expression of AQP9 was reverse correlated with arsenic trioxide sensitivity in leukemia cells." (PMID 37500645, 2023). "In vitro studies found that ATRA could increase the uptake of arsenic trioxide by leukemia cells through upregulating a transmembrane protein aquaporin-9 (AQP9), which is recognized as a major pathway of arsenic uptake." (PMID 37500645, 2023). "In this study, we hypothesize that G-CSF can increase the sensitivity of leukemia cells to ATO by upregulating the protein expression of AQP9." (PMID 35590355, 2022). "Understanding the mechanisms controlling AQP9 expression may enable pharmacological strategies to be designed to up-regulate AQP9 in leukemia cells, hence constituting a potential method to expand the therapeutic spectrum of As2O3 in the treatment of AML." (PMID 25953102, 2015). "When the leukemia K562 cell line was transfected with human AQP9 cDNA, trisenox uptake was found to increase, which may lead to leukemia cell death." (PMID 24959239, 2014). "In addition, AQP9 contributes to As(III) sensitivity in leukemia cells." (PMID 22489166, 2012). "For example, NB4 (one APL cell line) expresses the highest level of AQP9 and is most sensitive to As2O3, with the lowest IC50 value for arsenic among leukemia cell lines." (PMID 35967171, 2022). "Overexpression of AQP9, sensitized leukemia cells to metalloids, while As(III)-resistant leukemic cell lines displayed low level of AQP9." (PMID 22489166, 2012). "The mechanisms of how AQP9 is regulated in leukemia cells still remain not very clear." (PMID 35590355, 2022). "The involvement of AQP9 in leukemia has not been fully delineated." (PMID 24959239, 2014).
prostate carcinoma (10 papers, 2016 to 2025). A carcinoma that arises from epithelial cells of the prostate gland. "AQP9 is associated with enhanced androgen-independent prostate cancer progression by activating the ERK pathway and promoting cell proliferation, migration, invasion, and apoptosis." (PMID 40305202, 2025). "OncoPrint data analysis of prostate cancer patients further uncovers the possibilities of AQP1, AQP3, AQP5 and AQP9 being developed as prognostic biomarkers for prostate cancer." (PMID 36672280, 2023). "Even though AQPs including AQP1, AQP3, AQP5 and AQP9 have exhibited significant roles that contribute to prostate cancer prognosis, very little progress has been made in identifying AQPs as biomarker(s) for their use in prostate cancer." (PMID 36672280, 2023). "A research group evaluated and confirmed the androgen-dependent upregulation of AQP9 in prostate cancer." (PMID 36672280, 2023). "We can conclude that AQ9 accelerates prostate cancer progression in combination with the relatively high expression level of AQP9 in prostate cancer tissues compared with normal prostate tissues." (PMID 35972604, 2022). "Previous studies have shown that AQP9 induces the growth and the migration of prostate cancer and astrocytoma cells." (PMID 34012923, 2021). "For instance, the expression of AQP9 in prostate cancer was significantly increased compared with the adjacent tissues." (PMID 31969493, 2020). "Increasing studies have revealed the involvement of AQP9 in tumor progression: AQP9 has taken a part in the growth and migration of prostate cancer cells." (PMID 33247170, 2020). "PC-3 cell line was androgen-independent prostate cancer cell, therefore, we selected PC-3 initially transfected with AQP9 siRNA, and the knockdown efficiency was observed using RT-qPCR and western blot analysis." (PMID 27187384, 2016). "In this report, we addressed the functional role of AQP9 in androgen-independent prostate cancer cells invasion, tumor growth and metastasis, and providing an underlying mechanisms of the role of AQP9 in PCa progression." (PMID 27187384, 2016). "In the present study, AQP9 was determined in prostate cancer and adjacent cancer tissues; AQP9-siRNA was applied to silencing AQP9 in androgen-independent prostate cancer cell PC3 cell line." (PMID 27187384, 2016). "We first evaluated the expression level of AQP9 in two prostate cancer cells PC-3, LNCap by immunofluorescence, and Western blot." (PMID 27187384, 2016). "In this work, AQP9 was shown to be expressed in human prostate cancer cells, and AQP9 was silenced in androgen-independent prostate cancer cell line PC-3." (PMID 27187384, 2016). "To investigate the functions of AQP9 on prostate cancer, we knockdown its expression by RNA interference (RNAi)." (PMID 27187384, 2016). "From wound healing assay and matrigel invasion, we suggested that AQP9 expression affects the motility and invasiveness of prostate cancer cells." (PMID 27187384, 2016). "We then analyzed data of prostate cancer patients from GEO (Gene Expression Omnibus) dataset (Access ID: GSE55945) and found that AQP9 expression significantly increased in prostate cancer tissues compared with the adjacent tissues of patients." (PMID 27187384, 2016). "AQP9 expression also affects the motility and invasiveness of prostate cancer cells." (PMID 36672280, 2023). "AQP9 gene regulation occurs by estrogen response elements (ERE) in prostate cancer." (PMID 36672280, 2023). "Furthermore, a progressive decrease in the expression of AQP5 and AQP9 was observed during prostate cancer progression that negatively correlates with their expression." (PMID 36672280, 2023). "Specific targeted therapy with AQP9 might exert far-reaching significance in prostate cancer treatment." (PMID 35972604, 2022). "AQP9 upregulation in prostate cancer could enhance growth, migration, and invasion involving ERK1/2 signaling; reduced levels of phosphorylated ERK1/2 and MMP9 were observed in AQP9-deficient cell lines." (PMID 29922644, 2018).
prostate carcinoma (continued). "Moreover, we addressed the important role of AQP9 in prostate cancer progression to androgen-independent." (PMID 27187384, 2016). "Moreover, knockdown of AQP9 in PC3 androgen-independent prostate cancer cell prostate cancer cells increased inhibition rates of proliferation." (PMID 27187384, 2016). "In order to explore which pathways may be involved in AQP9-mediated motility and invasion of prostate cancer cells, the activation of ERK1/2 in PC-3 cells was examined." (PMID 27187384, 2016). "Our present study demonstrated that AQP9 regulates the expression of MMP9 in prostate cancer cells." (PMID 27187384, 2016). "Moreover, the results showed that inhibition of the ERK pathway decreased the expression of MMP9 in prostate cancer cells, suggesting that the ERK pathway is involved in AQP9-mediated MMP9 expression in prostate cancer cells." (PMID 27187384, 2016). "However, little is currently known regarding the function of AQP9 in androgen-independent prostate cancer cells." (PMID 27187384, 2016). "The effect of AQP9 on invasion of prostate cancer cell was further investigated." (PMID 27187384, 2016). "Furthermore, AQP9 could promote the proliferation, migration and invasion, whereas inhibit the apoptosis of prostate cancer cells." (PMID 31969493, 2020). "In addition, knockdown of AQP9 resulted in a significant decrease in the expression of the Bcl-2 and with a notable increase in the expression of Bax and cleaved caspase 3, indicated that AQP9 knockdown promoted apoptosis in prostate cancer cells." (PMID 27187384, 2016). "Thus, we suggested that AQP9 had proliferation-promoting properties in prostate cancer cells." (PMID 27187384, 2016). "A study explored the androgen-independent expression of AQP9 in prostate cancer PC3 cells, and in prostate cancer samples and adjacent cancer tissues." (PMID 36672280, 2023). "It is known that aquaporin 9 (AQP9) in the prostate was strictly upregulated by androgen and may represent a novel therapeutic target for several cancers, but whether AQP9 plays a role in the regulation of androgen-independent prostate cancer still remains unclear." (PMID 27187384, 2016). "The present study demonstrated that AQP9 knockdown in PC3 cells significantly decreased their invasion and motility capability; however, the exact pathway that AQP9 may regulate in prostate cancer remains unclear." (PMID 27187384, 2016). "Furthermore, the absence of AQP9 decreases anti-apoptotic protein Bcl-2 expression and increases apoptotic protein expression (cleaved caspase 3 and Bax) suggesting that AQP9 regulates apoptosis in prostate cancer." (PMID 36672280, 2023).
breast carcinoma (9 papers, 2018 to 2024). "AQP3 and AQP9 were associated with worse RFS in breast cancer patients." (PMID 36212456, 2022). "AQP1, AQP3, AQP4, AQP5, AQP7, and AQP9 expression were evaluated because these AQPs are expressed in breast tumors and have begun to be characterized as having roles in breast cancer progression and metastasis." (PMID 39123442, 2024). "In breast cancer patient datasets, AQP9 expression significantly correlated with specific markers, including eCD86 and CD115 (monocytes); CD68, IL10, and CCL-2 (TAMs); IRF5 and PTGS2 (M1 macrophages); and CD163, MS4A4A, and VSIG4 (M2 macrophages)." (PMID 36212456, 2022). "In breast cancer, AQP9 expression is positively correlated with immune infiltrates, such as B cells, CD4+ and CD8+T cells, neutrophils, macrophages, and dendritic cells (DCs)." (PMID 36212456, 2022). "Thus, ATO’s ability to inhibit breast cancer is positively correlated with Pin1 degradation and AQP9 expression." (PMID 30093655, 2018). "Moreover, a study found that breast cancer patients with high AQP7 mRNA expression had reduced overall survival (OS) compared to patients with low AQP7 mRNA expression and high AQP9 mRNA expression was associated with a worse relapse-free survival (RFS) and OS." (PMID 37681917, 2023). "Thus, the combination of AQP3 and AQP9 expression may contribute to increased MMP secretion in breast cancer." (PMID 37681917, 2023). "The role of Pin1 in mediating ATO’s anticancer activity is further supported by the findings that human breast cancer cells were differentially susceptible to ATO and highly correlated with the rate of ATO-induced Pin1 degradation and with the expression of the ATO transporter AQP9." (PMID 30093655, 2018). "A previous study performing transcriptomic analyses on breast cancer biopsies revealed increased mRNA expression of AQP1, AQP3, AQP5, AQP7, AQP9 and AQP11 when compared to overall median AQP levels in the biopsies." (PMID 37681917, 2023). "Transcriptomic analyses using the Human Protein Atlas database revealed higher mRNA levels of several AQPs in human breast cancer, namely AQP1, AQP3, AQP5, AQP7, AQP9 and AQP11, when compared to overall median AQP expression levels in the biopsies." (PMID 37681917, 2023). "The mRNA expression levels of AQP8, AQP9, and AQP10 were upregulated, while those of AQP3, AQP4, AQP5, and especially AQP7, were downregulated in breast cancer based on the Oncomine database." (PMID 36212456, 2022). "Eight cohorts of breast cancer (GSE1456, GSE1379, GSE1378, GSE4922, GSE12276, GSE7390, GSE3494, GSE11121) revealed that high expression level of AQP9 correlated with poor prognosis." (PMID 33247170, 2020). "Systematic analysis of how AQP7 and AQP9 affect the response of breast cancer cells to conventional anticancer therapies is still lacking." (PMID 37681917, 2023). "Transcriptomic analysis revealed that the three aquaglyceroporins, AQP3, AQP7 and AQP9, but not AQP10, are overexpressed in human breast cancer." (PMID 37681917, 2023).
lung carcinoma (9 papers, 2014 to 2022). "The result revealed that the higher AQP9 expression was determined to associate with worse prognosis in patients with breast or lung cancers." (PMID 33247170, 2020). "AQP9 enhanced the chemotherapy response and alleviated the chemotherapy resistance of arsenic during the treatment of lung cancer." (PMID 35972604, 2022). "We also analyzed the prognostic significance of AQP9 in patients stratified with different clinical characteristics in breast, gastric and lung cancers through the Kaplan–Meier plotter." (PMID 33247170, 2020). "The results demonstrated that the AQP9 expression was up-regulated in breast, colorectal and gastric cancers, while decreased in lung cancer compared with their normal tissues." (PMID 33247170, 2020). "Our results found that high AQP9 expression was significantly correlated with worse prognosis in breast, colon and lung cancers, while predicted better prognosis in gastric cancer." (PMID 33247170, 2020). "The results suggested that high AQP9 expression correlated with the prognosis of patients with lymphatic metastasis in breast, gastric and lung cancers." (PMID 33247170, 2020). "We found that the AQP9 expression level had significant impact on the prognosis in four types of cancers involving bladder, breast, colorectal and lung cancers." (PMID 33247170, 2020). "And two cohorts (jacob-00182-MSK, GSE31210) of lung cancer revealed that overexpression of AQP9 had poorer impact on the prognosis." (PMID 33247170, 2020). "The main polymorphisms on transporters OCT2, LRP, AQP2, AQP9 and TMEM205 genes were genotyped in 338 lung cancer patients." (PMID 24643204, 2014). "AQP9 was not only important to arsenic resistance in human lung cancer cells by enhancing arsenic uptake, but also play a critical role in development of platinum-based chemotherapy response." (PMID 24643204, 2014). "Thus, a high expression of AQP9 was significantly correlated with a worse prognosis in breast, colon and lung cancers, while predicted a better prognosis in gastric cancer." (PMID 34830779, 2021). "However, high AQP9 expression was significantly correlated with worse prognosis in breast, colon and lung cancers, while predicted better prognosis in gastric cancer both in diffuse and intestinal gastric cancer." (PMID 34012923, 2021). "In addition, the AQP9 expression in lung cancer had poorer impact on the prognosis of patients at stage N0 and stage N1." (PMID 33247170, 2020). "Recent studies have reported that impaired AQP9 expression may contribute to the development of numerous types of cancer, such as lung cancer and malignant brain tumour." (PMID 31969493, 2020). "The result suggested that AQP9 may play as an important biomarker that predicts poor prognosis for breast, colorectal and lung cancers and favorable prognosis for gastric cancer." (PMID 33247170, 2020). "Higher expression of AQP9 predicted worse prognosis for breast, colon and lung cancers." (PMID 33247170, 2020). "However, the mechanism how AQP9 play a role in platinum-based chemotherapy efficacy for lung cancer patients requires to be studied in the next work." (PMID 24643204, 2014). "In conclusion, the genetic polymorphisms in OCT2, AQP2, AQP9 and TMEM205 may contribute to chemotherapy response in lung cancer patients." (PMID 24643204, 2014). "However, the hazard ratio calculations for overall survival time of patients with lung cancer showed no convincing associations with expression levels of any classes of AQPs, apart from a possible small increase in hazard (HR 1.3) with AQP9, suggesting another area for future inquiry." (PMID 32679804, 2020). "Our results showed that SNPs rs195854 (OCT2) and rs186941 (OCT2), rs7314734 (AQP2), rs1516400 (AQP9), and rs896412 (TMEM205) might be related with chemotherapy response in lung cancer patients." (PMID 24643204, 2014).